BSND (barttin CLCNK type accessory subunit beta)
Description:
Regulatory subunit of anion-selective CLCNKA:BSND and CLCNKB:BSND heteromeric channels involved in basolateral chloride conductance along the nephron to achieve urine concentration and maintain systemic acid-base homeostasis, and in the stria vascularis of the inner ear to establish the endocochlear potential necessary for normal hearing. Most likely acts as a chaperone that allosterically regulates proper sorting of CLCNKA:BSND and CLCNKB:BSND channels at the basolateral plasma membrane domain and functional switch to ion conducting state. Mediates constitutive opening of channel common gates.
Synonyms: BART; DFNB73
Tractability: Antibody: UniProt places it where antibodies can reach, with high confidence; its Gene Ontology location is reachable by antibodies, with high confidence; UniProt predicts a signal peptide or a membrane-spanning region.
Gene: Protein-coding gene on chromosome 1 (54,998,933 to 55,017,172, forward strand). Ensembl gene ENSG00000162399.
Subcellular location: Basolateral cell membrane
Pathways (Reactome):
Transport of small molecules: Stimuli-sensing channels
Gene Ontology:
Molecular function: chloride channel regulator activity; protein binding; chloride channel activity
Biological process: chloride transport; chloride transmembrane transport; sensory perception of sound
Cellular component: basolateral plasma membrane; plasma membrane; protein-containing complex
Genetic constraint (gnomAD): Loss-of-function variants: 14 observed, 21.24 expected, observed/expected ratio (o/e) 0.66, 90% interval 0.43 to 1.03. The upper end of that interval is the gene's LOEUF score, 1.03, which puts it in group 4 of 6, group 1 being the genes least tolerant of losing a copy. Missense variants: 379 observed, 438.94 expected, observed/expected ratio (o/e) 0.86, 90% interval 0.79 to 0.94. Synonymous variants: 170 observed, 171.19 expected, observed/expected ratio (o/e) 0.99, 90% interval 0.88 to 1.13.
Gene-disease validity (ClinGen):
ClinGen rates the evidence that BSND causes each of these diseases.
Bartter disease type 4A (autosomal recessive): Definitive.
Homologues: Orthologues: chimpanzee BSND (97% identical), macaque BSND (91% identical), dog BSND (78% identical), rabbit BSND (75% identical), guinea pig BSND (72% identical), mouse Bsnd (71% identical), rat Bsnd (71% identical), pig BSND (59% identical), zebrafish bsnd (13% identical).
Diseases named in the same sentence as BSND in open-access papers:
BSND is named in the same sentence as 21 diseases in open-access papers, as found by Europe PMC text mining. Sharing a sentence is not in itself a finding about the gene and the disease. The quoted sentences say what the papers report.
Bartter syndrome (8 papers, 2015 to 2025). "Classical Bartter syndrome with sensorineural hearing loss (hyperprostaglandin E syndrome), or BS type IVa, is caused by loss-of-function mutations in the BSND gene, which encodes barttin, a β-subunit for ClC-Ka and ClC-Kb." (PMID 39273282, 2024). "Mostly, mutations in BSND can cause Bartter syndrome, associated with hearing loss and renal abnormalities, but DFNB73 has also been attributed to a mutation in BSND and causing nonsyndromic deafness." (PMID 26989561, 2016). "Whole-exome sequencing (WES) excluded pathogenic variants in renal tubulopathy genes including SLC12A3 (Gitelman syndrome), SLC12A1, CLCNKB, BSND, KCNJ1, MAGED2 (Bartter syndrome), and CASR, CLCNKA, KCNJ10 (hypokalemia-associated genes)." (PMID 40893942, 2025). "Bartter syndrome is classified into five major genotypes caused by mutations in different genes, namely SLC12A1, KCNJ1, CLCNKB, CLCNKA, BSND, and MAGED2." (PMID 38238844, 2024).
Bartter syndrome type 4 (7 papers, 2015 to 2022). A form of Bartter syndrome characterized by maternal polyhydramnios, premature delivery, salt loss, polyuria and sensorineural deafness, associated with hypokalemic and hypochloremic metabolic alkalosis, increased levels of plasma renin and aldosterone, and low to normal blood pressure. "Bartter syndrome type IV is caused by biallelic mutations in the BSND gene that encodes Barttin, or by molecular abnormalities affecting the two adjacent CLCNKA (encoding the chloride channel ClC-Ka) and CLCNKB genes." (PMID 35137195, 2022). "A mouse model with a mutation in BSND, which encodes barttin, shows Bartter syndrome type IV, a hearing impairment also thought to be caused by a low EP." (PMID 25674062, 2015). "Notably, the CLDN16 gene interaction network appears to be associated with Bartter syndrome type 4, which results from mutations in the BSND gene also affecting the trafficking and function of CIC-K channels." (PMID 31357502, 2019).
deafness (5 papers, 2014 to 2024). An inherited or acquired condition characterized by the complete loss of the ability to hear from one or both ears. "Patient B15 was identified to harbor a homozygous missense mutation c.22C> T (p.Arg8Trp) of BSND gene, which has been previously reported and was associated with a similar phenotype such as deafness and renal failure." (PMID 29254190, 2017).
Hypokalemia (3 papers, 2015 to 2025). An abnormally decreased potassium concentration in the blood. "Type IVa and IVb involve mutation BSND and CLCNKA genes, respectively, with polyhydramnios, sensory deafness, hypokalemia, and hypochloremic alkalosis as prominent features." (PMID 40666068, 2025).
Pendred syndrome (3 papers, 2018 to 2023). Pendred syndrome (PDS) is a clinically variable genetic disorder characterized by bilateral sensorineural hearing loss and euthyroid goiter. "Mutations in SLC26A4 may cause SNHL in DFNB4 and Pendred syndrome, and mutations in BSND can lead to DFNB73." (PMID 37289589, 2023). "In pendrin knockout (KO) mice, the CCD proteome was accompanied by strong downregulation of other IC markers like CLCNKB, BSND (Barttin), and VAA (vH+-ATPase), a configuration that may contribute to the salt-losing phenotype of Pendred syndrome." (PMID 35330743, 2020).
Bartter syndrome type 4a (2 papers, 2020 to 2023). "Furthermore, barttin CLCNK-type accessory subunit beta (BSND), historically associated with Bartter syndrome type 4a, has been identified to modify the severity of cystic kidney disease and renal failure progression in JBTS caused by CEP290 variants." (PMID 37628633, 2023).
adenocarcinoma of the lung (1 paper, 2015). "The results showed that BSND and ATP6V1G3 protein was not expressed in a total of 85 lung carcinomas, composed of 44 cases of squamous cell carcinoma of the lung and 41 cases of adenocarcinoma of the lung." (PMID 26091477, 2015).
lung carcinoma (1 paper, 2015). "Finally, to determine the expression levels of BSND and ATP6V1G3 in various types of carcinoma other than RCC and lung carcinoma, we examined the 95th percentile mRNA expression values of BSND and ATP6V1G3 in various types of carcinoma using data from the TCGA database." (PMID 26091477, 2015).
renal oncocytoma (1 paper, 2015). "BSND and ATP6V1G3 protein expressions were also detected in renal oncocytoma (13/14 cases, 92.9%) and in the distal nephron, including the collecting duct, in the normal kidney." (PMID 26091477, 2015).
carcinoma (1 paper, 2015). A malignant tumor arising from epithelial cells. "An examination of the mRNA expression data from the TCGA database also revealed that the mRNA expression levels of BSND and ATP6V1G3 were extremely low in various human carcinomas in this study." (PMID 26091477, 2015).
BSND also shares sentences with these, for which no sentence is quoted: Gitelman syndrome (2 papers); renal failure (2); Alkalosis (1); Bartter syndrome type 3 (1); benign tumor (1); hyperprostaglandin E syndrome (1); Hypomagnesemia (1); Nephropathy (1); renal tubular disease (1); squamous cell carcinoma of the lung (1); tumor (1).